CLU (clusterin)
Diseases named in the same sentence as CLU in open-access papers (continued):
Sharing a sentence is not in itself a finding about the gene and the disease.
diabetic retinopathy (7 papers, 2012 to 2021). "Past proteomic studies have shown clusterin levels to be reduced in the vitreous of diabetic retinopathy patients." (PMID 31110225, 2019). "Clusterin is believed to promote angiogenesis or vascular permeability, which contributes to the pathogenesis of diabetic retinopathy." (PMID 27280065, 2016). "In T2DM, a significantly increased level of plasma clusterin was found and clusterin might be an useful biomarker for detecting the early stage of diabetic retinopathy." (PMID 27516739, 2016). "In the retina, clusterin is shown to play a role in the protection of the blood–retina barrier and photoreceptors during age-related macular degeneration (ARMD), diabetic retinopathy, ischemic retinopathy, and other diseases." (PMID 34445296, 2021). "For example, clusterin has been reported to be a cytoprotective protein in oxidative stress-induced cell death in the retinal pigment epithelial (RPE) cells, hypoxia-induced injury, diabetic retinopathy, and cerebral ischemic injury." (PMID 28767729, 2017). "Therefore, clusterin may contribute to the pathogenesis of PDR, and further studies investigating the precise role of clusterin in diabetic retinopathy are needed." (PMID 22390717, 2012).
Hypertension (7 papers, 2015 to 2025). The presence of chronic increased pressure in the systemic arterial system. "To test it, we analysed the levels of proteins relevant for both hypertension (Endothelin 1) and proteostasis (Ubiquitin and Clusterin), and their putative associations with the different forms of protein aggregates (oligomers and fibrils)." (PMID 35626723, 2022). "Our data show that plasma levels of total Ubiquitin and Clusterin were similar in both groups, but reveal a positive significant association between Endothelin 1 and Ubiquitin in the plasma of individuals with hypertension." (PMID 35626723, 2022). "Overall, it seems that the human body has the capacity to cope with these changes in proteostasis during mild, controlled, stages of hypertension, potentially through an interlinked action of Ubiquitin and Clusterin." (PMID 35626723, 2022). "The upregulated circulating proteins in PE+ (AMBP, VTN, CLU, F2, PZP, APCS, and HBB) are involved in blood pressure regulation, extracellular matrix dynamics, and immune system function, highlighting the pathogenesis of this hypertensive disorder in the context of inflammation and immune defense." (PMID 40673030, 2025).
liver fibrosis (7 papers, 2012 to 2025). "Loss and overexpression of clusterin promoted and attenuated hepatic fibrosis after TAA injection, respectively." (PMID 31739636, 2019). "TAA injection promoted hepatic fibrosis in wild-type mice, and the loss of clusterin aggravated the fibrotic condition further." (PMID 31739636, 2019). "Loss of clusterin promoted hepatic fibrosis after TAA injection, whereas overexpression of clusterin significantly attenuated TAA-induced hepatic fibrosis." (PMID 31739636, 2019). "Since CLU overexpression has been extensively delineated in the elastic fibers involved in liver fibrogenesis in response to chronic liver injury, whether systemic production of CLU is associated with severity of liver fibrosis remains to be determined." (PMID 33184463, 2020). "This study provides further evidence that clusterin effectively reduces liver fibrosis under various experimental conditions." (PMID 40089787, 2025). "In contrast to these deleterious metabolic effects, clusterin has been shown to reduce hepatic fibrosis via stellate cell downregulation of the Smad3 signaling pathway." (PMID 33717095, 2021). "In a mouse model prone to non-alcoholic steatohepatitis (NASH) adipocyte CLU expression also paralleled an increase in liver fat, hepatic fibrosis, and steatohepatitis." (PMID 33717095, 2021). "Overall, these findings demonstrate that clusterin functions as a defense mechanism to prevent hepatic fibrosis." (PMID 31739636, 2019). "The results presented here demonstrate that clusterin reduces hepatic fibrosis by inhibiting the activation of HSCs and the Smad3 pathway." (PMID 31739636, 2019). "Subsequently, we confirmed the effect of clusterin on liver fibrosis using RT-PCR and western blot analyses." (PMID 31739636, 2019). "In this study, we investigated the effect of clusterin on liver fibrosis in mice and hepatic stellate cells (HSCs) using a thioacetamide (TAA)-induced liver fibrosis model." (PMID 31739636, 2019). "Dynamics of clusterin expression was validated in the context of human liver fibrosis." (PMID 40197391, 2025). "We previously demonstrated that clusterin inhibits liver fibrosis." (PMID 40089787, 2025). "We previously demonstrated that clusterin protects against hepatic steatosis and hepatic fibrosis." (PMID 40089787, 2025). "Our results, in agreement to these findings, suggested that upregulation of clusterin may act as a defense mechanism to prevent hepatic fibrosis." (PMID 37569584, 2023). "Of various molecules known to be involved in cholestasis and liver fibrosis, clusterin (CLU) exerting its extracellular chaperone-like activity implicated in homeostasis/proteostasis of extracellular proteins is gaining increasing interest as a possible mediator for fibrogenesis." (PMID 33184463, 2020). "Here, we examined whether clusterin had protective effects against hepatic fibrosis using in vitro and in vivo models." (PMID 31739636, 2019). "In addition, we found that clusterin attenuates hepatic fibrosis by inhibiting the activation of hepatic stellate cells and Smad3 signaling pathways." (PMID 31739636, 2019). "Overall, these data suggest that clusterin plays an important role in hepatic fibrosis." (PMID 31739636, 2019). "Next, the effect of clusterin on hepatic fibrosis was examined using clusterin KO mice." (PMID 31739636, 2019). "Thus, clusterin plays an important role in hepatic fibrosis." (PMID 31739636, 2019). "Clusterin was upregulated in the livers of human cirrhotic patients and in thioacetamide (TAA)-induced and bile duct ligation mouse models of liver fibrosis." (PMID 31739636, 2019). "In addition, clusterin was highly expressed in mice that underwent BDL, another model of liver fibrosis." (PMID 31739636, 2019).
lymph node metastasis (7 papers, 2011 to 2025). "The risk of recurrence, extrathyroidal invasion, and lymph node metastasis were all significantly correlated with the level of CLU expression (P = .021.021, and .004, respectively)." (PMID 40797389, 2025). "Fourth, tumor stage and lymph node metastasis were closely associated with CLU expression, and subgroup analysis based on these factors will increase the stringency of data synthesis." (PMID 32039450, 2020). "Clusterin expression was found to be associated significantly with lymph node metastasis (P = 0.006), perineural invasion (P = 0.042) and elevated preoperative serum carcinoembryonic antigen level (P = 0.048), respectively." (PMID 22799602, 2012). "In addition, clusterin positivity was found to be associated with preoperative serum carcinoembryonic antigen level, perineural invasion, and, most strongly, lymph node metastasis." (PMID 22799602, 2012). "However, the results of the present study indicate that clusterin expression is strongly associated with lymph node metastasis, which is one of the most potent prognostic indicators." (PMID 22799602, 2012). "Although not an independent prognostic factor, clusterin immunoreactivity can be used in conjunction with lymph node metastasis to predict survival in cases of pancreatic adenocarcinoma." (PMID 22799602, 2012). "PTC patients with lymph node metastasis showed significantly lower IHC scores for PROS1 (P < .001), CLU (P = .003), and LRG1 (P < .001) than patients without metastasis, respectively." (PMID 40797389, 2025).
male infertility (7 papers, 2018 to 2023). The inability of the male to effect fertilization of an ovum after a specified period of unprotected intercourse. "Many pathologies associated with neurodegeneration, carcinogenesis, metabolic diseases, and civilizational diseases (e.g., cardiovascular incidents and male infertility) have been described as causes of homeostasis disturbance, in which the glycan part of clusterin plays a very important role." (PMID 36071866, 2022). "Therefore, the analysis of clusterin concentration changes in seminal plasma may be an important element in the diagnosis of male infertility linked with lack or lowered count of sperm." (PMID 36071866, 2022). "Recently, a glycoprotein clusterin (CLU), one of the crucial seminal plasma glycoproteins, has been proposed as a male infertility marker, due to its significant role in sperm capacitation and immune tolerance in the female reproductive tract." (PMID 34575138, 2021). "Our review is based on literature research performed in the PubMed and Google Scholar databases using search terms and their combinations, including clusterin, clusterin glycosylation, glycoprotein glycosylation, cardiovascular diseases, metabolic diseases, male infertility, cancer, and neoplasm." (PMID 36071866, 2022). "Clusterin (CLU) was originally identified as an androgen/testosterone-repressed gene in the prostate and reduced CLU protein levels in testis have been linked to male infertility." (PMID 29456864, 2018). "Taking into account the fact that CLU possesses at least four N-glycosylation sites as well as the importance of glycosylation in the sperm–oocyte interactions, the exploration of CLU glycans expression seems to be an important direction of study concerning male infertility issues." (PMID 36142505, 2022). "Considering that fucose is one of the most important glyco-element of seminal clusterin, comprehensive studies concerning CLU fucosylation may contribute to the knowledge of the role of fucosylated glycans in the development of male infertility." (PMID 34341430, 2021). "The differences in serum CLU and FUT4 concentrations, and in the expression of core fucose and antennary fucose α1,2-linked in CLU glycans between the N group and other groups examined suggest that the disturbances in sperm count, motility, and morphology are not the only cause of male infertility." (PMID 34341430, 2021).
prostate tumor (7 papers, 2004 to 2024). "In this regard, suppression of clusterin in prostate tumor models with antisense oligonucleotides resulted in increased cell death, delayed tumor growth, and reduced metastasis." (PMID 31426412, 2019). "Overexpression of clusterin has been reported in several malignant tumors such as breast, lung, liver, kidney, colorectal, and prostatic tumors." (PMID 31426412, 2019). "We have shown previously that prostate tumour tissue expresses significantly lower levels of clusterin compared to adjacent normal prostate tissue." (PMID 15494717, 2004). "Using PCa cell lines from racially diverse prostate tumors, it was found that glucocorticoids upregulated two stress oncoproteins related to PCa therapeutic resistance, Clusterin (CLU) and lens epithelium-derived growth factor p75 (LEDGF/p75), while glucocorticoid inhibition blocked this effect." (PMID 36291899, 2022). "Moreover, expression level of chaperones like clusterin has been shown to correlate directly with the prostate tumor grade." (PMID 31426412, 2019). "Moreover, our 3′SRP identified other potential miR-200c-3p target genes that could be involved in radiation resistance, including CLU (clusterin), a protein that is overexpressed in radioresistant LNCaP prostate tumor cells." (PMID 39414799, 2024). "Clusterin expression is increased in mice lacking the tumor suppressor Nkx3-1 gene in the early stages of the prostate tumor." (PMID 31426412, 2019). "PC-3 prostate tumour cells were substantially more sensitive to clusterin expression than nonmalignant PNT1a cells, showing multiple phenotypic changes including cell cycle arrest and increased apoptosis." (PMID 15494717, 2004).
psoriasis (7 papers, 2014 to 2025). An autoimmune condition characterized by red, well-delineated plaques with silvery scales that are usually on the extensor surfaces and scalp. "However, little is known about how clusterin affects the inflammatory reactions associated with psoriasis." (PMID 37717073, 2023). "In addition, clusterin is thought to be a chaperone protein that, under the conditions of oxidative stress associated with psoriasis, is involved in binding and removing cellular debris from the extracellular space, thereby preventing inflammation and autoimmunity." (PMID 39684771, 2024). "Studies conducted in patients with psoriasis, which in up to 85% of cases precede the onset of PsA, documented that serum clusterin levels were significantly higher in psoriasis patients compared to healthy controls." (PMID 39684771, 2024). "Clusterin expression was higher in the skin samples from patients with psoriasis than in those from healthy controls." (PMID 37717073, 2023). "To better characterize the effect of clusterin on psoriasis-like skin inflammatory reactions, we performed histological analyses of dorsal skin sections obtained from clusterin−/− and WT mice treated with IMQ or VAS." (PMID 37717073, 2023). "Clusterin appears to be a promising therapeutic target, as it can attenuate not only the molecular process involved in psoriasis initiation, but also that of psoriatic plaque progression via IL-17." (PMID 37717073, 2023). "WT mice treated with IMQ showed definite psoriasis-like changes, including increased skin erythema, scaliness, and thickness on the backs and ears, compared to clusterin−/− mice treated with IMQ." (PMID 37717073, 2023). "Taken together, these results suggest that clusterin suppresses the expression of pro-inflammatory cytokines involved in the signaling pathways of both psoriasis initiation and plaque progression." (PMID 37717073, 2023). "Genetic silencing of clusterin in human keratinocytes inhibited the production of inflammatory cytokines involved in the initiation and progression of psoriasis." (PMID 37717073, 2023). "The mean clusterin-positive areas (% ± SEM) in the epidermis of the psoriasis and control groups were 8.21% ± 0.54% and 4.11% ± 0.73%, respectively." (PMID 37717073, 2023). "Clusterin expression was examined according to the severity of psoriasis, using skin samples from patients with psoriasis and healthy controls." (PMID 37717073, 2023). "Clusterin expression in the epidermis was significantly higher in the mild and severe psoriasis groups than in the control group (P < 0.001, control vs." (PMID 37717073, 2023). "The clusterin-positive area in the dermis of the mild psoriasis group was 6.95% ± 1.27%, while that in the severe psoriasis group was 6.91% ± 1.36%." (PMID 37717073, 2023). "There is a very limited number of studies that have analyzed the level of clusterin in patients with psoriasis." (PMID 32764517, 2020). "The hypothesized mechanism for this relationship is based on a compensatory and protective role that clusterin may play in psoriasis." (PMID 39684771, 2024). "Therefore, we examined the role of clusterin in skin inflammatory reactions in an IMQ-induced murine psoriasis model and in human patients with psoriasis." (PMID 37717073, 2023). "Additionally, clusterin levels in the epidermis of patients with psoriasis were higher than those in healthy controls, a phenomenon that correlates with psoriasis severity." (PMID 37717073, 2023). "We also examined clusterin expression in the skin tissues of patients with psoriasis." (PMID 37717073, 2023). "Skin samples were obtained from patients with psoriasis and healthy controls and subjected to immunohistochemical analyses to evaluate the differences in clusterin expression between the psoriasis and control groups (psoriasis group, n = 29; control group, n = 15)." (PMID 37717073, 2023).
psoriasis (continued). "Therefore, to examine the involvement of clusterin in the initiation of psoriasis, human keratinocytes transfected with clusterin or control small interfering RNA (siRNA) were cultured and stimulated with IMQ." (PMID 37717073, 2023). "Skin tissues of patients with psoriasis showed high clusterin expression." (PMID 37717073, 2023). "Moreover, clusterin expression was significantly correlated with psoriasis severity (P < 0.001, Spearman’s rho = 0.5821)." (PMID 37717073, 2023). "Elafin, clusterin, or selenoprotein P may act as biomarkers for psoriasis and comorbid metabolic diseases." (PMID 33804147, 2021). "The subgroup analysis of clusterin levels revealed that the presence of psoriasis (inflammation and oxidative stress) significantly elevated the level of clusterin; the level of clusterin was also higher in the no-MetS patients compared to the no-Mets controls." (PMID 32764517, 2020). "We analyzed the expression of two potential markers of psoriasis: clusterin and elafin." (PMID 32764517, 2020). "Interestingly, Th17 cells (a subset of CD4+ T cells), which play a crucial role in pathogenesis of psoriasis, exhibit a lower expression of clusterin and a higher expression of Bcl-2, which make them less susceptible to apoptosis." (PMID 32764517, 2020). "Hence, additional studies are required to understand the role of CLU as a novel molecule in psoriasis." (PMID 24803721, 2014). "However, the specific mechanism by which clusterin regulates the “gut–skin axis” remains unclear, as does the role of clusterin in human psoriasis comorbidities." (PMID 37717073, 2023). "Moreover, clusterin levels are increased in the skin tissues of patients with psoriasis." (PMID 37717073, 2023). "Also, siRNA-induced clusterin suppression alleviated the production of pro-inflammatory cytokines by human keratinocytes, which are important for the initiation and progression of psoriasis." (PMID 37717073, 2023). "Thus, clusterin could be related to the IL-17 inflammatory pathway, and clusterin antagonists could be good candidates for new therapeutic agents for psoriasis by blocking the IL-17 inflammatory pathway." (PMID 37717073, 2023). "Clusterin may serve as either a protective or aggravating factor in the pathogenesis of psoriasis." (PMID 32764517, 2020). "Collectively, our results suggest that clusterin modulates psoriasiform skin lesions, systemic inflammation (including colitis), and intestinal dysbiosis in an animal model of IMQ-induced psoriasis." (PMID 37717073, 2023). "The mean clusterin-positive area (% ± standard error of the mean [SEM]) in the epidermis was 7.66% ± 0.69% in the mild psoriasis group and 9.61% ± 0.72% in the severe psoriasis group." (PMID 37717073, 2023). "We demonstrated that the genetic deletion of clusterin relieved psoriasis-like skin inflammation, systemic inflammation, and colitis in short-, medium-, and long-term IMQ-induced murine psoriasis model." (PMID 37717073, 2023). "In conclusion, inhibition of clusterin decreased psoriatic skin inflammation, systemic inflammation, colitis, and altered the F/B ratio in an IMQ-induced murine psoriasis model." (PMID 37717073, 2023). "The psoriasis-like skin phenotype was less severe in IMQ-treated clusterin−/− mice than in IMQ-treated WT mice and was not apparent in VAS-treated mice." (PMID 37717073, 2023). "Therefore, we evaluated the role of clusterin in psoriatic skin inflammation, systemic inflammation, and colitis using a murine model of IMQ-induced psoriasis." (PMID 37717073, 2023). "Clusterin and elafin levels were higher in the patients than in the controls but did not correlate to the severity of psoriasis." (PMID 32764517, 2020).
renal cell carcinoma (7 papers, 2013 to 2024). "Clusterin, like Kim-1, is expressed on the tubular cells after kidney injury and is also induced in polycystic kidney disease, and renal cell carcinoma." (PMID 29091707, 2017). "In the case of renal cell carcinoma, CLU inhibition by custirsen improves sorafenib cytotoxicity." (PMID 38667280, 2024).